IL1B (interleukin 1 beta)
Diseases named in the same sentence as IL1B in open-access papers (continued):
Sharing a sentence is not in itself a finding about the gene and the disease.
asthma (continued). "IL-12p40 (p = 0.005), IL-13 (p = 0.04), IL-1β (p = 0.02), and IL-4 (p = 0.03) were increased in those with Easy-to-Control asthma." (PMID 28686637, 2017). "Pharmacological therapies using specific receptors IL-4, IL-5, TNF and IL-1β blockers are likely to constitute a considerable development in asthma management." (PMID 27536321, 2016). "Various studies have shown that Th type 1 (Th1)-related cytokines (interleukin [IL]-12 and IFN-γ), Th type 2 (Th2)-related cytokines (IL-4, IL-5, and IL-13), and proinflammatory cytokines (IL-1β, IL-6, and TNF-α) are associated with asthma." (PMID 25658604, 2015). "The gal-3/gal-3BP ratio and IL-1RA/IL-1β ratio were significantly reduced, while gal-3BP and IL-1β were significantly elevated in neutrophilic asthma compared with eosinophilic and paucigranulocytic asthma." (PMID 25616863, 2015). "Our findings also suggest that suppression of inflammasome activation and IL-1β by an asthma microenvironment promotes the fibrogenic potential of MWCNTs." (PMID 26091108, 2015). "The proinflammatory effect of IL-1β and the anti-inflammatory effect of IL-1RA in asthma have been documented in a number of human and animal studies." (PMID 25821855, 2015). "Patients with neutrophilic asthma have impairment in anti-inflammatory ratio of gal-3/gal-3BP and IL-1RA/IL-1β which provides a further framework for exploration into pathologic mechanisms of asthma phenotypes." (PMID 25616863, 2015). "The clinical diagnosis of asthma or COPD together with a single sputum cytokine (IL-1β cutoff) demonstrated a simple approach to segment asthma and COPD populations into 3 groups with distinct and consistent cytokine profiles." (PMID 25129678, 2015). "The involvement of IL-1β in an OVA-induced asthma model was demonstrated in attenuated airway hypersensitivity response (AHR) in IL-1α/β knockout mice and reduced airway eosinophilic inflammation and goblet cell hyperplasia in mice lacking the IL-1β receptor." (PMID 24671176, 2014). "IL-1β and MMP-9 promote subepithelial fibrosis, subepithelial collagen deposition and elastin fibre disruption in asthma and in COPD are associated with many of the histopathological features of emphysema." (PMID 23398985, 2013). "IL-1β is increased in the bronchial epithelium and macrophages of patients with asthma, and IL-1β is required for OVA-specific IgE production and induction of eosinophilic airway inflammation." (PMID 23671638, 2013). "Airway smooth muscle cell proliferation in asthma is regulated by the proinflammatory cytokines including IL-1β and TNF-α." (PMID 23388501, 2013). "Airway remodeling and AHR correlated with increases in pulmonary IL-1β, a pro-inflammatory cytokine involved in the pathogenesis of asthma that can induce AHR 25,26." (PMID 24117726, 2013). "We observed an increase in the level of IL-1β, IL-4, IL-5, IL-6, IL-8, and IL-10 in asthma patients as compared to the controls." (PMID 23226977, 2012). "The IL-1β has also been shown to induce aryl hydrocarbon receptor in murine model of asthma, in a dose and time-dependent manner." (PMID 23226977, 2012). "More macrophages express IL-1β in asthma and IL-1ra serum levels increase during asthma exacerbations." (PMID 22300506, 2012). "Previous studies have showed that proinflammatory cytokine IL-1β mediated inflammation is one of the central themes in asthma and sinusitis." (PMID 22558282, 2012). "Proinflammatory cytokines such as TNF-α and IL-1β are potent multifunctional cytokines in the pathogenesis of many inflammatory diseases, including asthma and rhinitis." (PMID 23253436, 2012). "For this reason, we have characterised the role of miR-146a during IL-1β-induced IL-6 and IL-8 release from primary HASM cells, which are known to contribute towards chronic inflammation associated with the development of asthma." (PMID 20525168, 2010).
asthma (continued). "In an animal model of asthma, persistent NF-κB activation in the bronchi is driven by granulocytes via IL-1β and TNF-α, which both induce IκB-β degradation, perpetuating the immune response in asthmatic airways." (PMID 20671916, 2010). "Acute hypoxia influences the neuroimmune system through the action of IL-1β under numerous conditions (asthma, chronic obstructive lung disease, sleep apnea and heart failure)." (PMID 21157520, 2008). "Nerve growth factor, which is closely associated with asthma, is released from lung fibroblasts at an increased rate when exposed to TNF-α and IL-1β." (PMID 21157520, 2008). "Increased expression of IL-1β has been detected in airway epithelial cells and alveolar macrophages of patients with asthma." (PMID 16359550, 2005). "Additionally, inflammasome activation and IL-1β signaling can contribute to the development of rhinovirus-induced asthma, depending on patients’ developmental status." (PMID 41011440, 2025). "Therefore, an increased level of IL-1β is a marker of more severe asthma, as it induces steroid-resistant neutrophilic inflammation and airway hyperreactivity." (PMID 41156007, 2025). "Additionally, compared to eosinophilic and pauci-granulocytic asthma, neutrophilic asthma has been shown to have higher levels of IL-1β." (PMID 40136649, 2025). "Indeed, patients with T2low asthma generally have high amounts of IL-1β and neutrophils in their sputum." (PMID 41145900, 2025). "IL-1β induces neutrophil inflammation and may also increase the expression of Th2-type cytokines, exacerbating asthma deterioration." (PMID 40636260, 2025). "Beyond asthma, IL-1β contributes to COPD, lung fibrosis, and lung cancer, suggesting that chronic HDM exposure may promote other inflammation-driven lung diseases through this axis." (PMID 41445736, 2025). "Furthermore, treatment with anti-IL-1β antibodies resulted in both inhibition of the IL-1β response and remission of clinical characteristics of steroid-resistant asthma, while IL-1β administration led to the restoration of these characteristics." (PMID 41156007, 2025). "Accordingly, elevated basal levels of IL-1β may contribute to the progression of equine asthma by amplifying airway inflammation through the promotion of neutrophil recruitment and activation." (PMID 40646891, 2025). "Additionally, exogenous IL-1β treatment reduced the RV-C-mediated asthma-like phenotype in immature mice." (PMID 41011440, 2025). "Type 2-high and type 2-ultra-high asthma again involve IL-4, IL-5, and IL-13, while type 2-low asthma, due to the lack of biomarkers, is described as a type with different mechanisms of disease, including IL-1β, IL-6, or neutrophil infiltration." (PMID 38785919, 2024). "C. chinensis seed methanol extract can reduce IL-6, TNF-α, NF-κB, COX-2, and IL-1β in asthma." (PMID 39263346, 2024). "Numerous studies implicate NLRP3 inflammasomes, IL-1β and IL-18 in the development of asthma." (PMID 39131161, 2024). "N-GSDMD, IL-18, and IL-1β were significantly increased in asthma group." (PMID 39554494, 2024). "In addition, IL1B was known to contribute to Th2 inflammation via activation and recruitment of multiple inflammatory cells such as eosinophils and mast cells in asthma." (PMID 38317239, 2024). "IL-1β plays a pro-inflammatory role in the pathogenesis of asthma." (PMID 38218943, 2024). "Furthermore, the cytokines regulated by NF‐κB, including IL‐1β, IL‐2, ICAM‐1, and VCAM‐1 are associated with obese asthma." (PMID 38286741, 2024). "Indeed, IL-1β was reported to promote lung neutrophilia in a mouse model of respiratory virus-induced asthma exacerbation." (PMID 38892358, 2024). "Multivariate analysis revealed that elevated IL-1β (5.6-fold increase in risk) and high expression of iNOS and vimentin (6.3 and 7.9-fold increase in risk) were significant risk factors for the development of comorbidity of PAR and asthma." (PMID 38167134, 2024).
asthma (continued). "In a murine model of severe, steroid-resistant asthma triggered by Chlamydia respiratory infection and ovalbumin-induced allergic airway disease, administration of anti-IL-1β antibody and NLRP3 inhibitor (MCC950) suppressed neutrophilic inflammation and reduced IL-1β production in the lung." (PMID 39194521, 2024). "The levels of IL-1β in sputum and bronchoalveolar lavage fluid were higher in patients with asthma than in normal healthy adults, suggesting that the NLRP3 inflammasome may be involved in respiratory inflammation." (PMID 38945951, 2024). "In addition, CARD11+ populations in ILC3s and LPS-stimulated IL-1β+CD16+ monocytes from the PBMCs of obese individuals with asthma were significantly greater than those of obese controls or nonobese individuals with asthma." (PMID 39672814, 2024). "Additionally, wedelolactone inhibited the IL-1α, IL-1β, IL-6 and IL-17a mRNA expression, which were related to neutrophilic predominant asthma." (PMID 38459541, 2024). "Consequently, targeting NLRP3 inflammasome when aiming at IL‐1β as a therapeutic target for severe asthma has proven to be effective." (PMID 38668995, 2024). "Similarly, we indeed observed that prestimulation of bronchial epithelium with A. alternata significantly increased RV-induced mature IL-1β secretion in controls and patients with asthma to the same level." (PMID 37087523, 2023). "Notably, heat inactivation of HDM revoked HDM-enhanced RV-induced secretion of mature IL-1β in patients with asthma and healthy controls." (PMID 37087523, 2023). "Classically-activated macrophages are known producers of both TNF-α and IL-1β in asthma." (PMID 37445635, 2023). "This evidence implies that elevated IL-1β in neutrophil dominant asthma may have a crosstalk effect on dexamethasone, which aggravates corticosteroids insensitivity in neutrophilic asthma." (PMID 36949482, 2023). "Furthermore, the gut microbiota exacerbated OVA-induced allergic asthma through the NLRP3/IL-1β signaling pathway in asthma model mice." (PMID 38029078, 2023). "The mRNA expressions of TLR4, MyD88, nucleotide-binding oligomerization domain-like pyrin domain-containing protein 3 (NLRP3), caspase-1, interleukin (IL)-18, and IL-1β in induced sputum cells of patients with asthma were upregulated and related to the mRNA expression of MUC1." (PMID 37880668, 2023). "In our study, we found ILC3s produced neutrophil chemoattractants including CXCL8, CXCL1, TNF-α and GM-CSF after IL-1β stimulation, suggesting ILC3s may mediate airway neutrophilia in asthma by release of neutrophil chemoattractants." (PMID 36949482, 2023). "We hypothesized that the ability for NLRP3 inflammasome priming and/or activation and IL-1β release are increased, and can be therapeutically inhibited, in immune cells from patients with severe asthma." (PMID 38044426, 2023). "We next performed analyses to determine whether increased IL-1β release induced by LPS + nigericin treatment severe asthma is different in males compared to females, or in obese compared to non-obese subjects." (PMID 38044426, 2023). "In addition, a preclinical model of OB and asthma showed a significant increase in airway hyper-responsiveness, airway inflammation, pro-inflammatory cytokine levels, mRNA expression of NLRP3 and IL1β in mice with OB, asthma, and lower 25(OH)D levels." (PMID 37867510, 2023). "Importantly, our study shows strong relationships between IL-1β release from PBMCs and asthma status." (PMID 38044426, 2023). "Additionally, sputum expression of NLRP3 and IL-1β mRNA correlated with increased neutrophil numbers, severity of airflow obstruction and reduced disease control in these asthma patients." (PMID 37598239, 2023). "Finally, we determined the effectiveness of MCC950 treatment in reducing NLRP3 inflammasome-mediated IL-1β release from PBMCs from patients with asthma." (PMID 38044426, 2023).
asthma (continued). "Furthermore, we show that increased LPS + nigericin-induced NLRP3 inflammasome-mediated IL-1β release from PBMCs from patients with severe asthma correlate with increased total eosinophil and neutrophil numbers in the airways." (PMID 38044426, 2023). "In our model, we also observed the production of epithelial-derived innate cytokines, that in addition to Th2 cytokines, make a great contribution to the inflammatory response in asthma, such as IL-1β, IL-6, and TNF-α, the latter being considered a marker of neutrophilic asthma." (PMID 36980265, 2023). "We next performed analyses to determine whether increased nigericin-induced NLRP3 inflammasome-mediated IL-1β release in asthma patients is different in males compared to females, or in obese compared to non-obese subjects." (PMID 38044426, 2023). "In addition, the content of IL-1β in serum and the cellular inflammatory factors in sputum and bronchoalveolar lavage fluid of asthma patients also increased compared with healthy people." (PMID 36248872, 2022). "Indeed, NETs can promote the secretion of IL-1β by macrophages in a mouse model of asthma and they have also been demonstrated to contribute to IL-1 activation and processing in vitro." (PMID 35911691, 2022). "Compared with the model group, Danlong Dingchuan Decoction effectively reduced the expression levels of TNF-α, IL-4, TGF-β1, IL-6, IL-8, and IL-1β in the lung tissue, reduced the release of inflammatory factors, alleviated airway inflammatory response, and relieved asthma symptoms." (PMID 35186104, 2022). "According to the prediction results of network pharmacology, IL-6, TNF, CXCL8, IL-10, IL-1β, and IL-4 may be the key targets of Danlong Dingchuan Decoction against asthma." (PMID 35186104, 2022). "For example, TNF-α and IL-1β synergize to promote airway hyperresponsiveness, which might partly underlie the role of TNF-α in asthma." (PMID 35281022, 2022). "Besides, increased mRNA expression of inflammasome sensors (NLRP1, NLRP3, and NLRC4) and increased cytokine IL-1β levels are observed in the sputum samples of patients with neutrophilic severe asthma." (PMID 36248872, 2022). "Besides IL-6, IL-1β is also among the factors inducing the differentiation of Th17 cells, which has also been shown to promote Th2 responses in murine models of asthma." (PMID 36233196, 2022). "Given this background, the NLRP3/caspase-1/IL-1β pathway apparently plays an important role in the pathogenesis of asthma, but the precise effects of NLRP3 inflammasome activation on airway inflammation in an OVA-induced murine model of neutrophilic asthma remain elusive and deserve investigation." (PMID 35664352, 2022). "MiR-146a may exacerbate the disease in asthma patients by increasing IL-1β production and miR-106a by decreasing IL-10 production." (PMID 36311189, 2022). "In addition, elevated levels of IL-1β were found in the sputum of patients with neutrophil-dominant severe asthma." (PMID 34064821, 2021). "Interestingly, during HDM-induced asthma, caspase-1 activation and IL-1β maturation were upregulated only in alveolar macrophages, not in neutrophils or DCs, indicating that AMs contributed most to HDM-induced inflammasome activation." (PMID 34413860, 2021). "The correlation between changes in lncH19 and miR-324-3p expression in specific pulmonary inflammatory diseases, such as asthma, needs to be studied in the future because our hypothesized mechanism is based on an IL-1β-induced epithelial cell model." (PMID 33413425, 2021). "In addition, PBNs obtained from patients with severe asthma were found to induce increased production of IL-1β, IL-6, and IL-8 in response to LPS plus S100A9, which further activated macrophages and AECs." (PMID 34285336, 2021). "Furthermore, we identified a new player, the NLRP3 inflammasome-mediated IL-1β, which can drive airway mucus overproduction in asthma (See Graphic abstract)." (PMID 34868022, 2021).
asthma (continued). "Furthermore, evidence from several animal asthma models has suggested that treatment with drugs that neutralize IL-1β reduces AHR, inflammatory cell infiltration, and the levels of TH2 cytokines." (PMID 33708257, 2021). "Upregulated miR-200a/200b expression could inhibit the ERK/MMP-9 pathway by targeting orosomucoid 1-like 3 (ORMDL3), reduce the secretion of TNF-α, IL-1β, -4, -5 and -13, and slow down the development of asthma-related inflammation." (PMID 34635022, 2021). "Similarly, the expression of IL-1β was increased in alveolar macrophages, while it remained unchanged in neutrophils and dendritic cells after asthma was induced." (PMID 34413860, 2021). "IL-1β was also confirmed to be involved in the viral stimulus-induced asthma exacerbation." (PMID 34344357, 2021). "Therefore, we wanted to further investigate the role of the proinflammatory cytokines IL-1β and IL-18 in mediating protection during asthma, because both cytokines are released on Nlrp1 activation." (PMID 33378691, 2021). "Ghrelin is expected to have anti-inflammatory actions that might suppress proinflammatory cytokines such as tumor necrosis factor (TNF)-α, IL-1β and IL-6, which are involved in the inflammation and pathogenesis of asthma." (PMID 32143340, 2020). "Inhibition of p38 MAPK might improve the corticosteroid insensitivity via modulating the release of IL-1b and IL-8 in patients with severe asthma." (PMID 32016112, 2020). "Previous studies revealed that IL-1β could reflect the acute inflammatory response in some pulmonary diseases such as asthma and ARDS." (PMID 32694925, 2020). "SC treatment significantly reduced the expression of IL1b and Tnf in lung tissues of asthma mice." (PMID 32016112, 2020). "Inhaled PM causes IL-1β secretion and further increases the thickness of conducting airways, mucus secretion, and lymphocyte accumulation in the airways, which can lead to COPD and asthma when persisted." (PMID 32650472, 2020). "There was increased expression of DNASE1L3 in asthma and IL1B in neutrophilic asthma." (PMID 31903716, 2020). "Furthermore, SC decreased the expression of inflammatory factors, including Tnf and IL-1b in lung tissues of asthma mice." (PMID 32016112, 2020). "One and 5 μg/ml BioPM collected from chicken, goat and pig farms induced the production of IFNγ, IL-10, IL-1β and TNFα by PBMCs from stable asthma patients and healthy volunteers in an apparent concentration-dependent manner (except for TNFα production induced by BioPM from the goat farm)." (PMID 32620109, 2020). "In study I, we confirmed the different clinical characteristics of EA, NA and PGA phenotypes, and as in previous studies showed that subjects with NA were older, had longer asthma durations, and higher sputum IL-1β, IL-8 and TNF-α, but lower FENO compared with EA." (PMID 31113430, 2019). "We agree and further propose that caloric restriction may be beneficial for asthma in obese individuals, possibly by suppressing the IL-1β response." (PMID 30670753, 2019). "Interestingly, Th17 response cytokines IL-17 and IL-1β were only elevated in RV-C-infected children with pre-existing asthma." (PMID 31703379, 2019). "However, Th17 response cytokines IL-17 and IL-1β were only elevated in RV-C-infected children with pre-existing asthma." (PMID 31703379, 2019). "Thus, antagonizing the function of IL-1β holds promise as a potential therapeutic option for the treatment of asthma." (PMID 31548841, 2019). "Release of interleukin-1β (IL-1β), and Il-6, as a pro-inflamatory stimulating cytokine, could be reduced significantly by SalA60, also in neutrophils in in vivo asthma mouse model." (PMID 31594975, 2019). "COPD and asthma patients have been shown to have increased baseline levels of IL-1β; thus, DUSP10 may have an increased role in a disease setting." (PMID 30333178, 2019).